CST3 (cystatin C)
Diseases named in the same sentence as CST3 in open-access papers (continued):
Sharing a sentence is not in itself a finding about the gene and the disease.
sarcopenia (continued). "In addition, eGFR values were measured including the endogenous biomarker cystatin C that may be more adequate in old age compared to creatinine, which is known to be confounded by sarcopenia." (PMID 37528401, 2023). "Therefore, more studies of sarcopenia in patients with CKD using cystatin C may be warranted to more accurately estimated kidney function." (PMID 37222019, 2023). "Therefore, the serum creatinine-to-cystatin C ratio (CCR) may be a promising alternative biomarker for sarcopenia." (PMID 37864250, 2023). "A single-center study of 215 cirrhotic patients on the LT waitlist developed the Sarcopenia HIBA score to predict sarcopenia using clinical variables: male sex, BMI, Child–Pugh score, and creatinine/Cystatin C ratio." (PMID 40871617, 2025). "For the present analysis, the use of the CKD-EPI cystatin C equation allows for a more tailored assessment of kidney function in MHD patients and remains a critical variable in our sarcopenia prediction model." (PMID 41262446, 2025). "The serum creatinine-to-cystatin C ratio (CCR) and the Sarcopenia Index (SI), both derived from SCr and cystatin C (CysC), provide simple and objective measures for evaluating muscle mass." (PMID 40104495, 2025). "Given that muscle weakness is considered a preliminary sign of sarcopenia, studies are required to investigate HGS with relevance to cystatin-c." (PMID 40095091, 2025). "Four indices were computed: predictive skeletal muscle mass index (pSMI), total-body muscle mass (TBMM), creatinine-to-cystatin C ratio (CCR), and sarcopenia index (SI)." (PMID 39634549, 2024). "Serum creatinine-to-cystatin C ratio (CCR) is a novel and simple tool which can be used as an index of sarcopenia." (PMID 35836165, 2022). "We examined the relationships between cystatin C-based GFR (eGFRcys), creatinine-based GFR (eGFRcre), their ratio (eGFRcys/eGFRcre) and sarcopenia in community-dwelling older adults in Japan." (PMID 33090338, 2021). "In present study, we evaluated the frequency of overestimated renal function, defined as a >20% higher eGFR using creatinine than using cystatin C, in 307 patients with CLD as well as its relationship with indicators of sarcopenia." (PMID 34371925, 2021). "Serum indices based on creatinine (Cr) and cystatin C (CysC), including Calculated Body Muscle Mass (CBMM), Sarcopenia Index (SI), and estimated glomerular filtration rate (eGFR) ratio, have emerged as potential biomarkers for sarcopenia." (PMID 40852370, 2025). "The ratio of serum creatinine and serum cystatin C (creatinine/cystatin C, known as CCR) as well as serum creatinine × eGFRcystatin C, known as the sarcopenia index (SI), have been recently indicated as possible predictors of sarcopenia." (PMID 38921440, 2024). "Creatinine-cystatin C ratio (CCR) has been demonstrated as an objective marker of sarcopenia in clinical conditions but has not been evaluated as an osteoporosis marker in individuals with normal renal function." (PMID 38836225, 2024). "Moreover, in studies on sarcopenia with CKD, it is desirable to accumulate studies using cystatin C to accurately estimate kidney function." (PMID 37222019, 2023). "They reported that there were significant differences in cystatin C‐based eGFR with and without sarcopenia, but not in creatinine‐based eGFR." (PMID 37222019, 2023). "We have previously reported the relationship between cystatin C (CysC), an indicator of renal function that, unlike creatinine (Cr), is not easily affected by muscle mass and sarcopenia in an epidemiological study at Hyogo Medical University." (PMID 37093792, 2023). "Among the many markers, serum cystatin C has been suggested as an alternative to creatinine in patients with presumed sarcopenia because it is not influenced by muscle mass." (PMID 37959364, 2023). "The serum creatinine/cystatin C (Cr/CysC) ratio has attracted attention as a marker for sarcopenia, but has not been studied in patients with idiopathic pulmonary fibrosis (IPF)." (PMID 35606777, 2022).
sarcopenia (continued). "Serum creatinine/cystatin C (Cr/CysC) ratio has attracted attention as a surrogate marker for sarcopenia but has not been adequately studied in patients with gastric cancer." (PMID 35045814, 2022). "The sarcopenia index based on serum creatinine and cystatin C can predict pneumonia rather than other postoperative complications among older patients after hip fracture surgery." (PMID 34641805, 2021). "Our study did not include the endogenous biomarker cystatin C, which is potentially more suitable for assessing renal function in older individuals compared to creatinine, as creatinine levels can be affected by sarcopenia." (PMID 38983263, 2024). "Furthermore, if there is sarcopenia, it would be preferable to perform a cystatin C test rather than a creatinine test to obtain an appropriate renal function result." (PMID 36530922, 2022). "However, SPS should only be diagnosed in the absence of non-renal factors influencing creatinine and cystatin C e.g. sarcopenia and glucocorticoid treatment." (PMID 35075286, 2022). "Additionally, there were no available data on cystatin C, which is less likely to be influenced by age-related sarcopenia in older adults." (PMID 32542048, 2020). "In conclusion, the sarcopenia index based on serum creatinine and cystatin C may not serve as biomarkers of either low muscle mass or sarcopenia in urban community-dwelling older people with normal kidney function." (PMID 30068907, 2018). "Also, in contrast to other studies, OPRA includes information on sarcopenia and glucocorticoid treatment, two significant non-renal factors affecting creatinine and cystatin C and which allows us to establish an accurate picture of eGFRcysC/eGFRcrea ratio in the general elderly population." (PMID 35075286, 2022). "Sixth, sarcopenic evaluation by BIA is not seemed to be cost-effective just for the cystatin C indication, but BIA could be utilized due to their increasing use in hospitalized patients for sarcopenia, frailty or nutritional assessment." (PMID 36530922, 2022).
Obesity (101 papers, 2011 to 2025). Accumulation of substantial excess body fat. "A higher cystatin C is associated, however, with inflammation and obesity, and restricting our analyses to individuals with well-controlled HIV aimed to limit confounding by HIV viremia." (PMID 39791983, 2025). "In women, higher risk during the pandemic was associated with obesity, angina, elevated cystatin C levels, and a history of COVID-19." (PMID 39774287, 2025). "The result is consistent with the previous research, which suggests that cystatin C is associated with insulin resistance, obesity, and metabolic syndrome." (PMID 37056689, 2023). "The restricted cubic spline model suggested that low or high cystatin C levels were associated with an increased risk of obesity in boys, whereas only higher cystatin C levels were associated with an increased risk of obesity in girls." (PMID 35185798, 2022). "In conclusion, this study suggested a U-shaped association between serum cystatin C levels and obesity in boys, with low or high cystatin C levels both associated with an increased risk of obesity." (PMID 35185798, 2022). "This study aimed to explore the association between serum cystatin C levels and obesity in adolescents of different sexes." (PMID 35185798, 2022). "The different associations we observed between the cystatin C levels and obesity risk of different sexes were interesting." (PMID 35185798, 2022). "Cystatin-c is associated with fat mass and inflammation, which in turn are related to conditions of severe obesity." (PMID 36295869, 2022). "The restricted cubic spline model analyzed the association between cystatin C levels and obesity in boys and girls." (PMID 35185798, 2022). "Many studies have been conducted on cystatin C levels in adults, but few on the association between cystatin C level and overweight or obesity in adolescents." (PMID 35185798, 2022). "Whereas in girls, the risk of obesity showed a trend of initially increase and then decrease with increasing cystatin C levels." (PMID 35185798, 2022). "Longitudinal studies should be conducted to further investigate the diagnostic potential of cystatin C in the progression of early obesity in adolescents of different sexes." (PMID 35185798, 2022). "The risk of obesity showed an increasing trend with elevated cystatin C levels before the cystatin C level reached 0.91 mg/L in girls, with the highest risk of obesity (OR = 1.07, 95% CI: 0.88–1.31) at the cystatin C levels of 0.91 mg/L." (PMID 35185798, 2022). "Analysis of the strength of association between each level of cystatin C quartile by sex and obesity defined by BMI as a criterion in adolescents." (PMID 35185798, 2022). "The present study proposed that the cystatin C level in adolescents was associated with obesity, particularly obesity defined by BMI." (PMID 35185798, 2022). "A U-shaped correlation was observed between serum cystatin C levels and the risk of obesity in boys." (PMID 35185798, 2022). "On the other hand, some studies have reported an association between obesity and elevated serum cystatin C levels." (PMID 24876964, 2014). "We recently found an association between obesity related phenotypes and rs2424577, a variant located in CST3, the gene that encodes Cystatin C, which is the main endogenous enzymatic inhibitor of Cathepsins." (PMID 22844403, 2012). "However, it differs by incorporating new indicators: number of painful body regions, left-hand grip strength, and cystatin C. Our findings reinforce established associations between depression, obesity, and ADL decline [21, 26-28, undefined, undefined]." (PMID 40537082, 2025). "Conversely, factors such as chronic inflammation (as indicated by insulin resistance), obesity, smoking, elevated levels of tumor necrosis factor and C-reactive protein, or lower serum albumin levels have been linked with higher serum cystatin C levels, leading to lower eGFRcys according to mGFR." (PMID 39125705, 2024).
Obesity (continued). "For instance, cystatin C levels are associated with obesity." (PMID 37079513, 2023). "Therefore, we hope that prospective studies with larger sample sizes will be followed to confirm the differences of different cystatin C levels with obesity risk among boys and girls." (PMID 35185798, 2022). "Thus, the primary goal of this cross-sectional study was to investigate the association between cystatin C and overweight or obesity in adolescence." (PMID 35185798, 2022). "The boys, had a trend of increasing obesity risk with increasing cystatin C levels." (PMID 35185798, 2022). "We used RCS to explore the dose-response association between cystatin C level and obesity." (PMID 35185798, 2022). "However, in girls, the risk of obesity showed a trend of initially increase and then decrease with increasing cystatin C levels." (PMID 35185798, 2022). "Further, some data suggested that increased cystatin C levels could be regarded as an early prognostic indicator of vascular risk in children with obesity." (PMID 35185798, 2022). "In contrast, in girls, obesity risk showed a decreasing trend with increasing cystatin C levels." (PMID 35185798, 2022). "There was a U-shaped association between cystatin C levels and obesity in boys, and the risk of obesity showed a trend of first decrease and then increase as cystatin C levels increased, and either low or high cystatin levels were associated with an increased risk of obesity." (PMID 35185798, 2022). "Regarding the strong U-shaped relationship between the risk of obesity and cystatin C levels in boys, the plot showed a decreasing risk trend in the lower range of predicted cystatin C levels, reaching a minimum risk around 0.97 mg/L and then increasing (Pnonlinear = 0.478)." (PMID 35185798, 2022). "Association between cystatin C levels and obesity as defined by three criteria: BMI, WC, and WHtR." (PMID 35185798, 2022). "Our findings showed that the metabolic components of abdominal obesity and low HDL cholesterol were determinants of cystatin C, and they were consistent with those of prior studies showing that cystatin C is associated with metabolic syndrome, obesity determined by BMI, and HDL." (PMID 33129312, 2020). "In subjects with severe obesity undergoing medical weight loss, estimating equations that use cystatin C and are indexed to actual BSA may provide a more accurate assessment of renal function." (PMID 32097414, 2020). "Interestingly, a study in patients with manifest arterial disease or CVD risk factors suggests that EV protein levels of cystatin C positively while CD14 negatively correlate with obesity and obesity-induced metabolic complications." (PMID 31277271, 2019). "Among the obesity-related markers, such as adipocytokines, inflammatory cytokines and polyunsaturated fatty acids, studied herein, a particularly strong association between cystatin C and EAT was revealed." (PMID 28922364, 2017). "Furthermore, it has been shown that in obesity, plasma EVs contain high amount of cystatin C and CD14, that have been correlated with high risk for myocardial infarction, vascular disease mortality and subsequent vascular events, in patients with vascular diseases." (PMID 33339409, 2020). "Considering cystatin C levels is therefore important when interpreting CatS activity, especially in metabolic conditions such as obesity and atherosclerosis." (PMID 41460824, 2025). "A significant inverse association was reported between OF consumption and the log of C-reactive protein concentration and log of cystatin-C concentration.,23 MetS prevalence, and BMI and obesity during childhood and adulthood." (PMID 39101594, 2025). "Multivariable MR results showed that obesity mediated the causal effect of OSA on eGFRcystatin c, BUN levels and serum cystatin C levels." (PMID 39928765, 2025).
Obesity (continued). "Due to the potential relationship between NGAL levels and obesity-related metabolic complications, we also evaluated cystatin C, another biomarker of kidney function, in obese patients with type 2 diabetes and subjects with MHO." (PMID 40004620, 2025). "There are biological and clinical aspects that limit the use of cystatin C, such as obesity, thyroid dysfunction, systemic inflammation, and corticosteroid treatment." (PMID 39713962, 2025). "In MR analysis, genetic predisposition to OSA was associated with decreased eGFRcystatin c, increased BUN and serum cystatin C levels in individuals with obesity." (PMID 39928765, 2025). "Notably, factors associated with increased mortality in women – such as obesity, angina, and elevated cystatin C levels – are also risk factors for death from COVID-19, supporting that women may be more vulnerable than men to complications directly related to the virus." (PMID 39774287, 2025). "Systemic inflammation, obesity, and being a smoker can result in increased cystatin C, whereas muscle mass and diet can affect serum creatinine." (PMID 41209168, 2025). "Pregnant women with obesity and generalized gingival bleeding exhibited notably higher expression of Cystatin-D (>4-fold), with slight increases in Cystatin-B (1.62-fold), Cystatin-C (1.49-fold), and Cystatin-SN (1.12-fold) compared with G2." (PMID 40366920, 2025). "Several factors such as obesity, chronic inflammation, thyroid disease, and steroid usage affect cystatin C levels." (PMID 37959364, 2023). "However, the assessment of renal function in the context of obesity and following marked weight loss is difficult, since the formulas adopted to estimate glomerular function use biomarkers whose production is dependent on muscle mass (creatinine) or adipose tissue mass and inflammation (cystatin-c)." (PMID 36295869, 2022). "Current smoking (14.1%), sleep (12.3%: 6.2% from short sleep duration and 6.1% from sleep disturbance), adiposity (9.8%: 4.9% from obesity and central obesity, respectively), HbA1c (10.7%) and cystatin C (5.5%) were identified as the main mediators." (PMID 34414428, 2022). "When compared to OWP, pregnant women with obesity and periodontitis showed a down-regulation of Cystatin-S, -SA, -SN, -B, and -D, while Cystatin-C was up-regulated." (PMID 36355174, 2022). "Current smoking, sleep disturbance, obesity, central obesity, HbA1c and cystatin C were chosen for the mediation analysis of incident CVD because of their associations with both shift work and outcomes." (PMID 34414428, 2022). "In obesity defined by the BMI, higher cystatin C levels were observed in adolescents with obesity (P = 0.005)." (PMID 35185798, 2022). "Cystatin-c, although initially promising, proved to be an imperfect marker for assessing kidney function in severe obesity." (PMID 36295869, 2022). "Prospective studies with larger sample sizes should be conducted to evaluate the value of cystatin C levels in predicting the progression of early obesity in adolescents of different sexes." (PMID 35185798, 2022). "The production of cystatin C in adipose tissue can lead to an increase in the concentration of cystatin C in the blood of children with obesity." (PMID 35185798, 2022). "body height, presence of obesity, mean arterial pressure, presence of dyslipidaemia, HbA1c, current smoking, cystatin C) for several CCM parameters indicated that RH-PAT remained as the only significant explanatory variable." (PMID 33935969, 2021). "Significantly higher concentrations of uric acid and cystatin C were observed in obesity group (p = 0.001; p = 0.028)." (PMID 34442019, 2021). "We obtained an increase in the serum concentration of cystatin C in stage 2 CKD with obesity, reflecting the state of glomerular filtration and the degree of renal function decrease." (PMID 33456602, 2020).